TNF (tumor necrosis factor)
Diseases named in the same sentence as TNF in open-access papers (continued):
Sharing a sentence is not in itself a finding about the gene and the disease.
infection (continued). "Given this, it is not surprising that TNF pathway was activated during K. pneumoniae infection and may play an essential role in clearing the infection." (PMID 36249423, 2022). "However, HK2 KO and HIF1A KO cells pretreated with TNFα fully restricted HCMV initiation of infection, indicating these factors are not necessary for TNFα’s anti-viral activity." (PMID 35834576, 2022). "At 24 h post-infection, cells were stimulated with or without TNF-α for 6 h." (PMID 36211339, 2022). "Likewise, a Cochrane systematic review on the down-titration and discontinuation of anti-TNF-α agents in patients with RA also did not report on the occurrence of infections or skin manifestations." (PMID 35625771, 2022). "WBCATH induced a subtle nonsignificant increase of TNFα after one and 24 h in non-infected macrophages, while a significant two-fold higher concentration of TNFα was determined after 24 of infection in macrophages incubated with WBCATH in comparison with the other groups." (PMID 36671276, 2022). "Moreover, increased release of tumor necrosis factor alpha (TNFα), interferon-gamma (INF-γ), and even interleukins produced during infection reduce the synthesis and secretion of lipoproteins, as well as alteration in the distribution of lipoproteins from intravascular to extravascular space." (PMID 35096202, 2022). "Furthermore, knockdown of Nek7 significantly inhibited the secretion of IL-1β, but the secretion of IL-6, TNF-α, and IL-1α were not affected during PmCQ2 infection." (PMID 35350616, 2022). "These non-infectious inflammatory conditions may result, for example, in the release of cytokines such as interleukin-1 (IL-1), interleukin-6 (IL-6), tumor necrosis factor alpha (TNF-α), and gamma interferon (INF-γ), which mask those specific to the inflammatory response to infection." (PMID 35208167, 2022). "TNFα remained unchanged in animals with or without infection." (PMID 35335632, 2022). "Although we observed higher frequencies of TNF-α-positive peripheral blood CD4+ T cells at the time of the first challenge in vaccinated compared to control animals, T cell activation was not correlated with the number of SHIV challenges required for infection." (PMID 35196125, 2022). "Furthermore, compared with the control group, vB_CbrM_HP1 administration resulted in a decrease in cytokine (TNF-α, IFN-γ, IL-1β) levels which was the same phenomenon as seen in the phage PIZ SAE-01E2 and the phage AVP in the treatment of infection with S. abortus equi and A. viridans, respectively." (PMID 35601403, 2022). "The higher concentrations of IL-8, IP-10 and TNFα (proinflammatory response) when compared to IL-4 or IL-10 (anti-inflammatory response) suggested a induction of proinflammatory response due to the infection in these TB-infected animals, regardless of the study group." (PMID 36439353, 2022). "Notably, patients with IBD treated with anti-TNFα did not elicit severe outcomes to infections, implying that not only B cell responses participate in the protection against SARS-CoV-2." (PMID 35893835, 2022). "In contrast, transcript expression of the TNF-α receptors TNFR1 (Tnfrsf1a) and TNFR2 (Tnfrsf1b) were not altered in the brain following infection, suggesting that enhanced TNF-α signaling in this setting is mediated primarily through induction of cytokine expression." (PMID 35462541, 2022). "In addition, infection of both SA14+ and SA14 induced the production of IL-8, IFN-γ, and TNF-α." (PMID 34986751, 2022). "However, infection or inflammation may amplify the action of LMW-HAs via interactions with hyaladherins, leading to an increase in the secretion of cytokines (TNF-α, IFN-β, IL-6), chemokines (IL-8), ROS, or enzymes (NE, MMP-9, MMP-10, MMP-12)." (PMID 35625586, 2022). "Importantly, TNFα secretion was not affected upon BMDMs infection with the TssL3-complemented V. proteolyticus strain." (PMID 36155655, 2022).
infection (continued). "Moreover, CD3-Σ chain and TNF were evaluated at the transcriptional level, and our results showed that the CD3-Σ chain increased significantly with BCG MOI 1, and it was observed at both 5 and 24 h post-infection (p < 0.01)." (PMID 35626672, 2022). "Regardless of CLR treatment, CFA+GLA-SE/CDG immunization significantly elicited Mav CFA-specific CD4+CD44+CD62 L− T cells producing IFN-γ+IL-17A+, and IFN-γ+TNF-α+ but not IFN-γ+IL-2+ in the lungs in the CFA+GLA-SE/CDG-immunized group compared with those in the infection control group." (PMID 35499090, 2022). "Notably, this only occurred when LECs were pretreated with TNFα, such that resting LECs did not promote productive infection." (PMID 34465136, 2022). "To more carefully assess whether TNF-α signaling was required for ZIKV-mediated alterations to neurologic gene expression, we cultured primary cortical neurons and pretreated with neutralizing antibodies against cytokine receptors for 2 h prior to infection." (PMID 35462541, 2022). "In the early stage of infection, the host produces a T helper type 1 (Th1) response against migrating immature and mature parasites, which involves secretion of Th1-type cytokines, such as interleukin (IL) -12, interferon-γ (IFN-γ), and tumor necrosis factor-α (TNF-α)." (PMID 35756064, 2022). "Whether infection in the absence of SP-A modulates TNF expression via different or modified NF-κB-mediated pathways under other conditions, is currently unknown." (PMID 35844510, 2022). "Functional analysis highlighted a relation to proinflammatory signalling pathways, including TNF-α signalling, interleukin signalling and chemotaxis via GPCR signalling, overall suggesting an increasing recruitment and cell adhesion of these immune cell populations upon infection." (PMID 35501398, 2022). "Also, patients on tumor necrosis factor (TNF) inhibitors and/or corticosteroids did not have a higher incidence of infection." (PMID 35987619, 2022). "Additionally, positive TNF-α+, IFN-γ+, and IL-4+ mCD4+ T cells could still be detected in the infection-only group." (PMID 36494338, 2022). "As in the case of TNF-α, the ΔpyrC mutant strain-infected U937 cells showed significantly higher levels of IL-1β and IFN-β production than the wild-type strain, and pyrC complementation decreased these levels to that observed upon infection with the wild-type strain." (PMID 36389167, 2022). "Again, in line with our hypothesis of exaggerated responses to lung infection, many of the top upstream regulators identified by IPA were associated with enhanced inflammation (TNF, IFNG, and IL1B) and infection with Gram-negative bacteria (TLR4)." (PMID 36264633, 2022). "This difference, observed in the current study, may be due to the type of patient samples used (serum vs nasal swabs) and suggest that the downregulation of the key cytokines, IL-2, IL-6, TNF-α, and IFN-γ, occurs in the nasopharyngeal milieu during the early infection." (PMID 36584119, 2022). "The infection of A549 and SK-OV-3 with HAdV26 induced changes in the expression of the IL-6, IL-8, IL-1β, and TNF-α genes; namely the expression of all four genes was increased in HAdV26-infected A549 cells, while HAdV26 infection resulted in increased expression of IL-6 and TNF-α in SK-OV-3 cells." (PMID 35458402, 2022). "Thus, TNF, ILs, and IFN play vital roles in the occurrence and development of infection." (PMID 34490839, 2021). "This does not exclude a role for TNF however: TNF may act in its membrane-inserted form, or infection may sensitize cells to TNF-signaling." (PMID 34711816, 2021). "Analyses of the cytokine production (MCP-1 and TNF), macrophage infiltration (estimated by Adgre1 (F4/80) expression), and Nos2 (iNOS) induction in the infected lungs detected a higher expression of Ccl2 (MCP-1), Adgre1, and Nos2 in Trem2−/− mice than in WT mice at day 3 after infection." (PMID 33863908, 2021).
infection (continued). "This suggests that promoting neutrophil secretion of TNF early in infection may help control CFU growth; that neutrophil secretion of TNF remains a significant (although less influential) parameter during the adaptive response suggests that this benefit persists during the adaptive response." (PMID 34675916, 2021). "Strikingly, infection with NTSNΔinlF triggered significantly higher production of cytokines IL-6 (p <0.05) and IL-1β (p <0.05) in the spleen; there was no obvious difference in TNF-α elicited by three Lm strains (p >0.05)." (PMID 35223532, 2021). "Multicolor flow cytometry was utilized to analyze the CD4+ and CD8+ T cell populations and their intracellular production of the cytokines IFNγ, TNF, and IL2 (single, double, and triple combinations) associated with both the lethal and nonlethal murine models of infection." (PMID 34287349, 2021). "Finally, and similar to our in vitro observation, TNF without infection increased the amount of bystander cell death in the cornea, fully recapitulating the death decision speed vs accuracy tradeoff." (PMID 34016976, 2021). "Thus, an early and consistent TNF-α response was observed in the low dose group while a delayed but a more robust TNF-α response in both Mtb-specific CD4+ and CD8+T cells was observed in the high infection dose." (PMID 34484203, 2021). "Studies have shown that dexamethasone can inhibit tumor necrosis factor (TNF) production by macrophages and promote the phagocytosis of microparticles by human monocytes, thereby played an important role in immune-mediated tissue damage or tissue repair after infection." (PMID 34435047, 2021). "The production of cytokines associated with pregnancy complications (premature birth and infections of the placental/fetal unit) was also increased in L. monocytogenes-infected trophoblasts (CCL2, CCL3, IL-8, CSF2, IL-1α/β, IL-1RA, IL-10, GM-CSF, IL-6, and TNFα)." (PMID 34367171, 2021). "Similarly to previously published work, the expression of the inflammatory cytokines (IL-1β, IL-6, IL-8, and TNF-α) after RVFV infection was upregulated to a greater extent in the absence of the RVFV NSs protein." (PMID 34835071, 2021). "There are indications that SAA plays multiple roles in infection, but since the serum values were close to homeostasis and because no related cytokines (IL-1, IL-6, and TNFα) are differentially expressed in the liver, the observed changes were not likely to be a direct response to an infection." (PMID 34679062, 2021). "TNF-α, an inflammatory cytokine belonging to tumor necrosis factor/ tumor necrosis factor receptor (TNF/TNFR) cytokine superfamily, plays key role in biological functions, such as the maintenance of homeostatic balance and immune function, and resistance capacity to infection and cancers." (PMID 34938756, 2021). "Thus, the induction and inhibition of TNF-α and IL1-β produced by mint oils controls the inflammatory response to inflammation against infection and might be beneficial to the host." (PMID 34201645, 2021). "The MALT1 inhibitor also did not affect the macrophage’s production of IL-6 and TNFα following L. pneumophila infection whether examined at the early 9-h time point or at 12, 24, and 48 h post infection." (PMID 34280250, 2021). "Functional polarization was most evident for IFNγ-producing MAIT cells, with TNF-producing MAIT cells displaying a similar but less pronounced pattern and the abundance of GM-CSF-producing MAIT cells increasing throughout the infection in all organs, except for the kidney." (PMID 34272362, 2021). "Here, we investigated the early transcriptional response of MDM to infection by single or aggregated Mtb and observed that infection with aggregates upregulates the TNFα gene network to a greater extent than infection with single or non-aggregated multiple Mtb per cell." (PMID 34925266, 2021).
infection (continued). "In correlation with q-PCR data, no expression of IFN−α; TNF-α, and IL-6 could be observed upon infection of mDC, M1-, and M2 macrophages with SARS-CoV-2." (PMID 34122407, 2021). "Notably, TNF‐α, IL‐1, and IL‐6 were not greatly induced in the intestine of the PDCoV single infection group and mock, whose level was significantly lower than that in both PRRSV infected groups." (PMID 33797313, 2021). "In the brainstem, it was observed an increase of pro-inflammatory cytokines, such as IL-1β, IL-12(p70), IL-13, and TNF-α; chemokines, such as CCL2, CCL3, CCL4, CCL11, CXCL10, and CXCL1; growth factors, such as G-CSF, GM-CSF, M-CSF, and anti-inflammatory IL-10 at ten days post-infection." (PMID 33917837, 2021). "T-cell derived cytokines (especially TNF-α and IFN-γ) are reported to induce the antimicrobial functions of macrophages, such as reactive oxygen and nitrogen intermediates, and help them to combat infection by facultative intracellular pathogens such as Y. pestis." (PMID 33669472, 2021). "Moreover, data showed that LP17 not only abrogated the significant difference in IL1β and TNFα expression, but also eliminated the apparent difference in CCL2 and CXCL10 expression between both groups of S. typhimurium-infected mice at 3 days post-infection." (PMID 33475464, 2021). "Intestinal macrophages isolated from mice in the absence of infection or inflammation do produce low levels of cytokines classically described as proinflammatory, such as TNF and IL6, in response to TLR stimulation but, crucially, they also produce IL-10 to temper their activity." (PMID 33465156, 2021). "Type-I T cells produced type-I cytokines, such as IL-2, TNF-α, and IFN-γ, to enhance cellular response to remove infected cells, whereas Type-II T cells produced type II cytokines, such as IL-4, IL-5, and IL-10, to increase antibodies to attack exogenous antigen to prevent host-cell infection." (PMID 34200327, 2021). "Furthermore, greater expression of IL-1β, TNF, and IL-8 was still observed during infection with PAO1 than PA14 with or without the presence of CFTR(inh)-172." (PMID 33664232, 2021). "Importantly, TNF stimulation never occurs in isolation, and upon infections, TLRs and inflammasomes are activated, leading to the production of a range of cytokines." (PMID 34663829, 2021). "IL-2, IL-6 and TNF-α were all induced to significantly lesser extents in the cortexes of the infected TLR4mut mice compared with the infected TLR4WT mice at day 4 PI, but they were induced to similar levels in the brains of both genotypes by VEEV TC-83 infection at days 2, 6 and 8 PI." (PMID 33487119, 2021). "Moreover, TNFα pre‐treatment of HMVEC‐L did not result in increased nucleocapsid protein‐positive cells upon infection with 6 × 104 PFUs of SARS‐CoV‐2." (PMID 34721846, 2021). "The absence of TNF-α did not impair viral clearance of either infection." (PMID 33680987, 2021). "However, MCF-treated macrophages showed a slight decrease in TNF-α levels within 4–28 hours after infection but were still higher than those in untreated noninfected macrophages (t = 20.611, P < 0.05)." (PMID 33680221, 2021). "In all MHV68 mice without manipulation of lungs, infection drove detectable levels of TNF." (PMID 34237078, 2021). "Additionally, tumor necrosis factor-alpha (TNF-α) and interleukin-1 alpha (IL-1α) production in tonsillar tissue cultures increased upon infection with human immunodeficiency virus-1 (HIV-1), which was found to have an impact on both innate and adaptive immune response." (PMID 33481814, 2021). "The levels of serum ALT, AST, liver IL-6, TNF-α, and IL-1β mRNA and liver pathological injury scores were further increased when pretreated with recombinant IL-27 in WT mice, but these levels were decreased in IL-27r−/− mice after CLP-induced severe infection compared to WT mice." (PMID 33564275, 2021).
infection (continued). "Furthermore, the initial proinflammatory cytokines, such as TNF-α, IL-6, and IL-1, produced in virus-infected cells may further activate NF-κB in adjacent cell populations to facilitate enhanced TMEV infection and replication." (PMID 34067536, 2021). "Combined in vivo and in vitro experiments comprising mice lacking OTUB1 specifically in liver parenchymal cells (OTUB1LPC-KO) and human OTUB1-deficient HepG2 cells revealed that OTUB1 prevented hepatocyte necroptosis but not apoptosis upon infection with Lm and DGal/TNF challenge." (PMID 33712742, 2021). "In fact, higher TNF-α and IL-6 production was observed in vitro by stimulating, with inactivated yeasts of C. albicans, equal numbers of total red blood cell (RBC)-lysed cells from the bone marrow and the spleen of mice 7 days after the primary infection compared to cells from uninfected mice." (PMID 34975887, 2021). "Also, TNF levels in BALF were significantly lower in Lysmcre-Btkfl/Y mice as compared to controls (p<0.05) 3 hours after D39 infection, whereas IL-6, CXCL1 and CXCL2 levels were not altered." (PMID 34552589, 2021). "As the TNF-α secretion by hMDMs upon Sporothrix species infection was not inhibited by blocking CR3, we further investigated the possible participation of other PRRs already described to mediate TNF-α release by human PBMCs infected with Sporothrix species morphotypes." (PMID 34867977, 2021). "Routinely, viruses are often identified post-infection by pattern recognition receptors (PRRs), such as the inflammasome sensor NLRP3, which trigger the production of interferons (IFNs) and inflammatory cytokines (e.g., IL-1, IL-6, and TNF) and initiate a local/systemic response to infection." (PMID 34572585, 2021). "Activation of TLR/TNF signaling during infection, combined with multiple expressions of apoptosis‐regulatory proteins, could also promote necroptosis indicating the phosphorylation of MLKL during BMDM infection." (PMID 34977874, 2021). "RT-qPCR and Western blot analysis showed that the levels of IL-1β, IL-6, TNF-α, and iNOS increased and mRNA and protein levels of TGM2 decreased in liver tissues of HFD-fed mice in comparison to control mice, while opposite results were observed by the further infection of AAV8-anti-miR-9-5p." (PMID 35261562, 2021). "Indeed, miR-155 functions as a positive TNF-α regulator in a fine-regulated self-sustaining miR-155/TNFα regulatory loop, which ensures high and stable levels of TNF-α during the initial phase of infection." (PMID 34069740, 2021). "The cytokine analysis of the child showed no significant increase in IL-6 and TNF, suggesting that the presence of a complex heterozygous CARD9 mutation may lead to decreased antifungal immunity and a susceptibility to TM infection." (PMID 34234782, 2021). "The pro-inflammatory cytokines produced during the innate IR are tumor necrosis factor-alpha (TNF-α) and IL-1, which stimulate the expression of endothelial adhesion molecules, favoring the accumulation of neutrophils, macrophages, bloodborne dendritic cells, and NK cells to the site of infection." (PMID 34946179, 2021). "As early as 2 h after initiation of transwell coculture, significantly higher levels of TNF-α were measured in supernatant fluids from THP-1 cells cultured with SL-null P. gingivalis compared to the parent (P < 0.05), a trend that was maintained through the 24-h infection period." (PMID 33361202, 2021). "Remarkably, we found higher TNF, IL-1β, IL-6, and IL-10 in lung homogenates of LysM-cre × Hif1αfl/fl mice when compared with Hif1αfl/fl control mice at 12 hours after inoculation; these differences were not present anymore at 40 hours after infection." (PMID 34393650, 2021). "Moreover, after removing individuals with genital inflammation from the analysis, 11 of the biomarkers remained significantly higher in the pre-infection group compared to the uninfected group (Fractalkine, GMCSF, ITAC, IL-1ß, IL-6, IL-7, IL-8, IL-21, MIP-1α, MIP-3α, and TNFα)." (PMID 33731158, 2021).